NGFR (nerve growth factor receptor)
Diseases named in the same sentence as NGFR in open-access papers (continued):
Sharing a sentence is not in itself a finding about the gene and the disease.
cancer (continued). "Therefore, by weakening the inhibitory effect of p73 on cancer cell growth through NGFR, we found that the new mechanism of CMA positively affects cancer cell survival." (PMID 37509689, 2023). "It would be interesting to test how PDK1 affects markers of cancer persisters, such as KDM5B and NGFR, and whether the knockdown cells are still capable of stochastic phenotypic switching." (PMID 32483452, 2020). "Furthermore, we aimed in the present study to evaluate the expression of nestin, NGFR, Sox10, FZD6 and PROM1 cancer stem cell markers and angiogenic factors in UM and to better understand the relationships between the detected markers and vasculogenic mimicry patterns." (PMID 33255843, 2020). "Altogether, our data demonstrate that overexpression of NGFR in tumors may serve as a mechanism by which cancer cells hijack the negative feedback regulation of p73 by NGFR for selective growth advantage." (PMID 32285119, 2020).
neurodegenerative disease (29 papers, 2011 to 2025). A disorder of the central nervous system characterized by gradual and progressive loss of neural tissue and neurologic function. "In mammalian brain, the age-dependent downregulation of NTRK1/NTRKA and p75/NGFR results in a reduced response of the cholinergic neurons to neurotrophic factors and is thought to play a role in the pathogenesis of neurodegenerative diseases." (PMID 32575701, 2020). "The age-dependent regulation of NTRK1/NTRKA and p75/NGFR in mammalian brain results in a reduced response of the cholinergic neurons to neurotrophic factors and is thought to play a role in the pathogenesis of neurodegenerative diseases." (PMID 32575701, 2020).
infection (23 papers, 2013 to 2025). The state of being infected such as from the introduction of a foreign agent such as serum, vaccine, antigenic substance or organism. "Total cells were first gated for NGFR expression as a marker of infection, and then Timer-FP positivity among infected cells (NGFR + ) was analyzed by flow cytometry over time." (PMID 38509308, 2024). "Some post-infection up-regulated processes such as nerve growth factor receptor pathway, response to peptide hormone and regulation of MAPK cascade are related to cell signaling and could, theoretically, being activated to sustain host cell survival." (PMID 31961876, 2020). "FSL1 and NGFR succeed IL-2 as the top 3 remarkably increased cytokines rejection vs infection." (PMID 30696462, 2019).
psychiatric diseases (5 papers, 2017 to 2023). "Increasing evidence based on animal studies found that genetic variants in NGFR could alter the brain’s susceptibility to psychiatric disorders." (PMID 36291307, 2022). "We found significant associations between NGFR and schizophrenia and that Ngfr may contribute to the social behavior of adult mice in the functional study, which provided meaningful clues to the pathogenesis of psychiatric disorders." (PMID 36291307, 2022). "It is possible that the NGFR gene is directly involved in one or some behavioral phenotypes that take different proportions in different populations with psychiatric disorders, resulting in varying protein levels." (PMID 36291307, 2022). "Previous research showed that NGFR is involved in neurogenesis, regulation of sprouting, synaptogenesis and pruning, which contributes to altered neural functions, and is thought to be the basis of psychiatric disorders." (PMID 36291307, 2022). "Rs11466162 is located at the 3′UTR of NGFR, which may affect psychiatric disorders by cooperating with other SNPs to form undetected haplotypes or regulate protein expressions." (PMID 36291307, 2022).
retinopathy (3 papers, 2019 to 2024). "In a mouse model of oxygen-induced retinopathy that mimics proliferative DR, NGFR-dependent inflammation leads to ischemia and pathological angiogenesis via Semaphorin 3A." (PMID 39347501, 2024).
lung (1 paper, 2020).
NGFR also shares sentences with these, for which no sentence is quoted: diabetes (25 papers); neurological disorders (14); cognitive decline (11); memory impairment (11); osteosarcoma (11); osteoarthritis (10); brain injuries (9); ischemia (9); Parkinson disease (9); squamous cell carcinoma (9); amyotrophic lateral sclerosis (8); esophageal cancer (8); liver fibrosis (8); retinal degeneration (7); alcohol (6); Arthritis (6); dementia (6); esophageal squamous cell carcinoma (6); glaucoma (6); metastatic melanoma (6); Obesity (6); autoimmune disease (5); diabetic retinopathy (5); epilepsy (5); head and neck cancer (5); injury (5); metastatic disease (5); rheumatoid arthritis (5); Cerebral ischemia (4); Hyperglycemia (4).
A further 212 diseases each share a sentence with NGFR in 4 papers or fewer.